IDO1 (indoleamine 2,3-dioxygenase 1)
Diseases named in the same sentence as IDO1 in open-access papers (continued):
Sharing a sentence is not in itself a finding about the gene and the disease.
breast carcinoma (continued). "It was guessed that IDO1 could promote local invasion of cancer cells, which leads to a worse outcome in other cancers, but it was less affected in breast cancer, which was rarely fatal through local invasion unless metastasis occurs." (PMID 36212460, 2022). "Therefore, reducing the expression level of IDO1 contributed to inhibiting the proliferation of breast cancer." (PMID 36550159, 2022). "Furthermore, STAT3-mediated IDO1 expression was found to be upregulated in breast cancer cell-induced MDSCs, which suppressed effector T cells and hyperactivated the infiltration of the Foxp3+ Tregs in TME." (PMID 33957948, 2021). "Notably, MDSCs-produced IDO1 favors Foxp3 + Tregs and tumor-induced immunosuppression, which in turn leads to advanced breast cancer clinical stage." (PMID 33957948, 2021). "Therefore, we aimed to develop a reliable and validated protocol for measuring of IDO1 activity in the popular ovarian (SK-OV-3) and breast cancer cells (MDA-MB-231)." (PMID 33541164, 2021). "The results showed that the predictive scores had a significant positive correlation with the immune checkpoints, such as PD1, PD1L2, and was particularly highly correlated with CTLA4, LAG3, and IDO1, suggesting immune regulation plays a key role in the prognosis of breast cancer chemotherapy." (PMID 34526986, 2021). "Increased TILs were described with reduced proliferative suppression in neoadjuvant, endocrine-treated, postmenopausal, ER+ breast cancer with increased levels of immune checkpoint components IDO1, PD-1 and LAG3 described with AI-resistant proliferation in luminal B cancer." (PMID 32825588, 2020). "Interestingly, we found that PD‐L1 and LAG3 were highly positive related to IDO1 in gynaecologic and breast cancers, but their correlation was reduced in normal breast tissue, ovary and uterus/cervix." (PMID 32227579, 2020). "Due to the low number of cases positive for IDO-1 manual assessment in the tumour only, stroma only and whole core was the most optimal method using a (0 = 0%, 1 = 1–33%, 2 = 34–66%, 3 ≥ 66%) scoring system reported for IDO-1 assessment in breast cancer tissue." (PMID 32487090, 2020). "Jacquemier et al29 also showed a positive correlation between IDO1 and TILs in breast cancer." (PMID 32227579, 2020). "We found IDO1 was significantly up‐regulated in four gynaecologic cancers and breast cancer." (PMID 32227579, 2020). "Interestingly, IDO1 showed an inverse correlation with oestrogen response in breast cancer, while the positive correlation in uterine carcinoma." (PMID 32227579, 2020). "The T cell activity studies revealed that controlled regulation of IDO1 enzyme activity in the presence of these potent compounds could induce immune response against breast cancer cells." (PMID 31804586, 2019). "Since TSP1 contain a high percentage of tryptophan, we speculated that the vascular IDO1 acts as a critical negative regulator of the tumour suppressive activity of stromal TSP1 in human breast cancer." (PMID 29156701, 2017). "Also, myeloid-derived suppressor cells isolated from patients with breast cancer express IDO1 in a STAT3-dependent manner." (PMID 24903009, 2014). "In mouse models of breast cancer, IDO1 inhibition with 1-methyltryptophan had only limited therapeutic effects in monotherapy, but the antitumour activity of this compound was enhanced when it was given in combination with classical cytotoxic agents such as paclitaxel." (PMID 22108515, 2012). "In addition to IDO1, breast cancer may show the concurrent expression of other immunosuppressive and tumor-promoting factors, which can even involve the kynurenine-AHR-axis." (PMID 39061522, 2024). "However, in ERα+ breast cancer, the IDO1 promoter is silenced through hypermethylation, thus suggesting that ERα expression on breast cancer cells might impact their response to microenvironmental stimuli through epigenetic reprogramming." (PMID 39282472, 2024).
breast carcinoma (continued). "Thus, in rabbits with mammary carcinomas, IDO1 may also be secreted and could initiate systemic immunosuppressive effects." (PMID 39061522, 2024). "Notably, IDO1 expression exhibits considerable variability across different tumors, with some immunohistochemical studies suggesting IDO1 positivity rates of 94% in uroepithelial carcinoma, 57-66% in ovarian cancer, 37-46% in breast cancer, 44-81% in renal cancer and 8% in GBM." (PMID 39678512, 2024). "Therefore, IDO1 and IDO2 may serve as promising immunotherapeutic targets in breast cancer, as IDO inhibition can enhance antitumor immunity and thereby restore cancer immunosurveillance." (PMID 37408267, 2023). "IDO-1 appeared only once among our included breast cancer articles, in a study where researchers analyzed the immunogenomic profiling and pathological response to neoadjuvant therapy including docetaxel and carboplatin, both commonly used in the treatment for breast cancer." (PMID 37181043, 2023). "An RNAseq analysis of invasive breast cancer specimens from the TCGA highlighted a negative correlation between IDO1 and ESR1 gene expression, along with a significant downregulation of IDO, specifically in luminal A and B BC subtypes." (PMID 37894728, 2023). "High mutational burden in ER+ HER2− breast cancer, and ERV3-2 expression in ER− HER2− and HER2+ breast, colon, and endometrial cancers are also associated with over-expression of all three IDO pathway genes, so these features may predict benefit from IDO-1 inhibitors." (PMID 34367262, 2021). "Furthermore, the IDO1 and immune cells network depicted a comprehensive landscape of tumour‐immune cell interactions, cell lineages and their effects on the overall survival of patients with gynaecologic and breast cancers." (PMID 32227579, 2020). "We used an objective, in situ assay to measure IDO1 in a collection of hormone receptor-positive breast cancers (HR+ BC)." (PMID 29037255, 2017). "Furthermore, CXCL9 and IDO1 have been shown to be prognostic markers in breast cancer." (PMID 24495478, 2014). "We further validated the expression of three key genes in breast cancer cell lines (MDA-MB-231 and MCF-7) and normal breast cells (MCF-10 A) via RT-qPCR and found that IDO1 is significantly overexpressed in MDA-MB-231 cells." (PMID 40217479, 2025). "Loading the IDO1 inhibitor NLG919 onto this biologically active gel system has shown promise in reversing immune suppression and significantly improving anti-breast cancer chemotherapy outcomes (Ref." (PMID 40040508, 2025). "Based on the TCGA-TNBC dataset analysis, four out of the five model genes (SDS, RDH12, IDO1, and GLDC) demonstrated significantly elevated expression levels in breast cancer samples." (PMID 40217479, 2025). "Collectively, these results indicate that IRF5 promotes tryptophan metabolism in breast cancer cells and facilitates metastasis by transcriptionally upregulating SLC7A5 and IDO1." (PMID 41179282, 2025). "Analysis of breast cancer data from the TCGA database revealed a strong positive correlation between IRF5 expression and that of SLC7A5 and IDO1." (PMID 41179282, 2025). "Furthermore, it has been shown that breast cancer may express not only IDO1, but also IL4I1." (PMID 39061522, 2024). "A recent analysis of unselected breast cancers in the UALCAN database also reported favorable prognostic effects of TIGIT and IDO1 expression." (PMID 37057719, 2023). "Basal and TNBC subtypes of breast cancers overexpressed CD274 conjointly with three ferroptosis drivers: TNFAIP3, IFNG and IDO1 (IDO1: inhibitory immune checkpoint)." (PMID 38201582, 2023). "Here, we investigated the effect of thiosemicarbazide derivatives, previously identified as dual inhibitors targeting topoisomerase IIα and indoleamine-2,3-dioxygenase 1 (IDO 1), on two distinct types of breast cancer cells (MCF-7 and MDA-MB-231)." (PMID 36982886, 2023).
breast carcinoma (continued). "A higher expression of IDO1 was found in the TNBC subgroup of the METABRIC cohort, as compared to other breast cancer samples (p-value < 2.2 × 10−16)." (PMID 38201582, 2023). "Indoleamine 2,3-dioxygenase 1 (IDO1) is upregulated in different types of cancers including lung cancers, ovarian cancers, prostate cancers, colon cancers, breast cancers, and kidney cancers." (PMID 36686754, 2022). "We developed a spectrophotometric assay to screen a library of 31 model ion transport-targeting compounds for potential effects on IDO1 function in A549 lung and MDA-MB-231 breast cancer cells." (PMID 35150740, 2022). "Compared with liposomal MTO, the immune response was significantly enhanced by co-delivery an IDO-1 inhibitor in IDO-overexpressed cancers, such as renal cancer (RENCA) and breast cancer (4T1 and EMT6)." (PMID 35524277, 2022). "IDO1 inhibitors for melanoma, glioblastoma, NSCLC, pancreatic and breast cancer are under investigation by pharmaceutical companies and sponsors." (PMID 34053179, 2021). "Several genes, such as IDO1, IL10 and CSF2, have been noticed to have positive correlation with HIST1H1B, and we chose CSF2 that plays critical roles in breast cancer aggressiveness to further analyze its links with HIST1H1B." (PMID 34746019, 2021). "Immunohistological staining for IDO1 in tumor sections indicated that the NCI-H69 small cell lung cancer and MDA-MB231 breast cancer markedly differed in their IDO1 expression levels, with higher IDO1 expression observed in the NCI-H69 than in the MDA-MB231." (PMID 34148865, 2021). "To evaluate the different responses to immunotherapy among the subtypes, we analyzed the mRNA expression of breast cancer immune checkpoint genes, namely PD-1, PD-L1, PD-L2, LAG3, VTCN1, IDO1, and TIM3." (PMID 34277633, 2021). "Similar to IDO1, TDO suppresses T cell activation by tryptophan depletion and is also overexpressed in the microenvironment of various tumors, including breast cancer." (PMID 33747948, 2021). "We investigate the antitumor potential of PDT combined with indoleamine 2,3-dioxygenase 1 (IDO) inhibitor in the murine 4T1 and E0771 orthotopic breast cancer models." (PMID 32107566, 2020). "According to breast cancer PAM50 classification scheme, IDO1 expression was higher in tumours of basal than other subtypes and shown better survival prognosis to BRCA and OV." (PMID 32227579, 2020). "According to breast cancer PAM50 classification scheme, IDO1 expression was higher in tumours of basal than other subtypes and showed better survival prognosis in BRCA and OV." (PMID 32227579, 2020). "mRNA expression of IDO1, IDO2 and HLA-G5 in breast cancer patients were respectively 2.9, 1.6 and 2.2 fold more than normal individuals, although these differences were not statistically significant (P=0.17, 0.85 and 0.81, respectively)." (PMID 28367424, 2017). "Previous studies have identified IDO1 as a favorable prognostic indicator for ER+ but not ER– breast cancer." (PMID 40663402, 2025). "In contrast to breast cancer, PD-L1 but not IDO-1 expression was high in the OAC immune-high/DDIR-positive cohort indicating potential differences in the immune microenvironment between the two tumour types." (PMID 39395265, 2024). "IDO1 is highly expressed and promotes metastasis, drug resistance, cell proliferation, and TAM resistance through STAT3 and interleukin-6 in TAM-resistant breast cancer." (PMID 38539263, 2024). "For this type of hormone receptor negative breast cancer, animal models with spontaneous mammary carcinomas would be most valuable, and the majority of pet rabbit mammary carcinomas represent IDO1-positive, ER-α-negative, and cold tumors." (PMID 39061522, 2024). "Additionally, IDO1 and IDO2 are upregulated in many tumors, including breast cancer, and the overexpression of IDO1 has been found to be associated with poor prognosis." (PMID 36765782, 2023).
breast carcinoma (continued). "Based on cBioportal analysis, we found that the overall survival time of breast cancer patients with one gene mutation in PRKDC, NOS2, ARG1, or IDO1 was significantly shorter compared with patients without the mutations." (PMID 36373232, 2023). "Importantly, in line with our previous study, we found higher expression of VISTA and IDO1 in primary LUAD and BM-LUAD as compared to breast cancer, with a predominant higher expression in primary tumors." (PMID 38149244, 2023). "In conclusion, breast cancer and pancreatic cancer are two distinctive cancer types with several common characteristics in aspects of gene, hormone, and inflammatory biomarkers such as IL-6, CD4 or CD8 cells, VEGF and IDO-1." (PMID 37181043, 2023). "IDO1 can down-regulate NKG2D and NKG2DL in NK cells by upregulating miR-18a, a microRNA (miRNA) that significantly promotes tumor cell growth, metastasis and inhibit apoptosis in breast cancer, ovarian cancer, lung cancer, and hepatocellular carcinoma." (PMID 35681736, 2022). "In turn, EOS200271, the novel, selective, non-competitive, orally bioavailable IDO1 inhibitor, demonstrated a potent antitumor effect in the breast cancer animal model." (PMID 34201791, 2021). "Furthermore, studies on targeting tryptophan catabolism enzymes, such as indoleamine-2,3-dioxygenase (IDO1/IDO2), and tryptophan-2,3-dioxygenase (TDO/TDO2), which are expressed by many immune cells and solid tumors, including breast cancer are underway." (PMID 33747948, 2021). "We found IDO1 expression was positively correlated (Spearman R > .3) with 271 genes in four gynaecologic cancers plus breast cancer, while no negatively correlated genes (Spearman R < −.3) appeared simultaneously in those cancers." (PMID 32227579, 2020). "The UALCAN analysis showed that only CXCL12 had a lower expression level in basal-like (triple-negative) breast cancer compared with luminal-like breast cancer, while CXCL5, IDO1, MIF, PTGS2, and VEGFA all had increased expression levels in basal-like breast cancer." (PMID 31293831, 2019). "Our result showed that IDO1, IDO2 and HLA-G5 had higher mRNA expressionsin ASCs isolated from breast cancer patients than those from normal individuals (P>0.05).mRNA expression of these molecules were higher in ASCs isolated from breast cancerpatients with stage III tumors than those with stage II." (PMID 28367424, 2017). "Using the JASPAR algorithm to predict transcription factor binding sites, we detected IRF5 binding motifs within the promoter regions of SLC7A5 and IDO1, suggesting that IRF5 may transcriptionally activate these genes, thereby enhancing tryptophan metabolism in breast cancer cells." (PMID 41179282, 2025). "Notably, none of the examined 96 pet rabbit mammary carcinomas contained IDO1-positive mononuclear immune cells, stromal cells, or endothelial cells." (PMID 39061522, 2024). "Numerous studies have reported that IDO1 is expressed and correlated with prognosis in various cancers, such as urothelial bladder cancer, non-small–cell lung cancer (NSCLC ), esophageal squamous cell carcinoma, breast cancer, pancreatic cancer, endometrial cancer, and neuroendocrine skin cancer." (PMID 36212460, 2022). "Further studies have shown that the expression of IDO1 was correlated with the expression of CD4, CD3, and CD8 as well as prognosis in colon cancer, but the expression of IDO1 was not related to the expression of CD3 and CD8 in the hormone receptor-positive breast cancer." (PMID 35187162, 2022). "We analyzed the levels of PD-L1 and IDO1 in all subtypes of breast cancer and found that expression of IDO1 in cancer tissues were higher in para-cancerous tissues at basal like (TNBC) positive breast cancer from the Gene Expression Profiling Interactive Analysis (GEPIA)." (PMID 34381711, 2021).
breast carcinoma (continued). "Likewise, in chromosome 8, arm-level gains of 8q and losses of 8p in human breast cancer SCNAs were further segmented into three amplification peaks involving STK3, MYC, and PTK2 and three deletion peaks involving CSMD1, PSD3, and IDO1 in hg19-aligned CMT SCNAs, respectively." (PMID 32680987, 2020). "The difference of the IDO1 protein levels in two breast cancer cell lines, MDA-MB-231 and MDA-MB-436, suggests that the constitutive expression of cellular IDO1 might not be associated with the tissue origin of cancer cells." (PMID 31324754, 2019). "Exposure of 4T1 mammary tumors to [neratinib + valproate] for three days resulted, two weeks later, in tumors that expressed less ERBB1, K-RAS, N-RAS, indoleamine-pyrrole 2,3-dioxygenase (IDO-1), ornithine decarboxylase (ODC) and had increased Class I MHCA expression." (PMID 29464055, 2018). "In addition, mRNA expressions of IDO1, IDO2 and HLA-G5 in breast cancer patients with pathological stage III were respectively 2.9, 607 and 113.7 fold more than ASCs compared to stage II, however this differences were not statistically significant ( P=0.32, 0.14 and 0.17, respectively." (PMID 28367424, 2017). "In the current study, we performed IHC analyses on ER– breast cancer biopsies to determine whether the spatial distribution of tumor NOS2 and COX2 contributes to immune-suppressive mechanisms involving TRegs, PD1/PDL1, IDO1, and B7H4 to suppress T effector (TEff) cell function." (PMID 40663402, 2025). "A treatment can be quite effective in a specific subset without being effective in the whole cancer type, e.g., Herceptin is very effective in HER2+ breast cancer but not effective in breast cancer overall, so it is important to identify the subsets of cancers that may benefit from IDO-1 inhibitors." (PMID 34367262, 2021). "Several studies investigated the expression of IDO1 in tumor tissue and cancer cells; however, the role and the expression of IDO2 are not well studied in breast cancer." (PMID 37408267, 2023).